IFI16 (interferon gamma inducible protein 16)
Diseases named in the same sentence as IFI16 in open-access papers (continued):
Sharing a sentence is not in itself a finding about the gene and the disease.
psoriatic arthritis (2 papers, 2022). Joint inflammation associated with psoriasis. "Regarding inflammatory‐related disorders, the serum levels of IFI16, as well as anti‐IFI16 antibodies, were elevated in psoriatic arthritis (PsA), which was more pronounced in patients with high CRP levels." (PMID 35832835, 2022).
triple-negative breast carcinoma (2 papers, 2024 to 2025). An invasive breast carcinoma which is negative for expression of estrogen receptor (ER), progesterone receptor (PR), and human epidermal growth factor receptor 2 (HER2). "For example, IFI16 has shown promise in inducing a STING-mediated immune response in triple-negative breast cancer (BRCA)." (PMID 39185402, 2024).
Zika virus infection (2 papers, 2019 to 2023). "Interestingly, IFI16 also exerted its antiviral activity against Zika virus (ZIKV) infection, the global threat re-emerging virus can cause microcephaly in humans." (PMID 31423125, 2019). "In addition, our results appeared extendable to other arbovirus as we found IFI16 also exerted its antiviral activity against ZIKV infection." (PMID 31423125, 2019). "In order to investigate effects of IFI16 on CHIKV and ZIKV infection, IFI16-overexpressed and silenced human skin fibroblasts were used as a model." (PMID 31423125, 2019).
acute tubular necrosis (1 paper, 2026). "Here we report that the levels of IFI16 and its mouse ortholog p204 were elevated in the kidney of patients with acute tubular necrosis (ATN) and in TECs of mice with renal ischemia/reperfusion (I/R)-induced AKI (I/R-AKI)." (PMID 41872158, 2026).
acute-on-chronic liver failure (1 paper, 2018). Acute-on-chronic liver failure (ACLF) is an extreme condition during the natural history of chronic HBV infection, with a relatively high short-term mortality. "Our study sought to identify a correlation between IFI16 expression and inflammation in patients with chronic hepatitis B (CHB) and HBV-associated acute-on-chronic liver failure (HBV-ACLF)." (PMID 29743020, 2018).
AIDS (1 paper, 2014). A syndrome resulting from the acquired deficiency of cellular immunity caused by the human immunodeficiency virus (HIV). "Sensing of reverse transcripts by IFI16 in quiescent CD4+ T cells induces cell death, which is thought to contribute to CD4+ T cell loss and progression to AIDS 73,74." (PMID 24782340, 2014).
alpha-thalassemia/mental retardation syndrome X-linked (1 paper, 2022). "ICP0 induces the degradation of chaperone proteins of histone H3.3 including interferon gamma inducible protein 16 (IFI16) and alpha-thalassemia/mental retardation syndrome X-linked (ATRX), resulting in attenuation of epigenetic silencing of viral genes." (PMID 35516420, 2022).
apical periodontitis (1 paper, 2024). "They observed that IFI16 protein expression peaked early after apical periodontitis induction, while the expression of IFN-α/β receptors was highest when the disease was fully established." (PMID 39723289, 2024).
arbovirus infection (1 paper, 2019). A viral infection that is transmitted by an arthropod. "Taken together, this study provides the first evidence of an antivirus activity of IFI16 during in vitro arbovirus infection, thus expanding its antiviral spectrum that paves the way to further development of antiviral drugs and vaccines." (PMID 31423125, 2019). "We extend herein these findings about the antiviral activity of IFI16 to arbovirus infection." (PMID 31423125, 2019).
autism spectrum disorder (1 paper, 2014). A spectrum of developmental disorders that includes autism, and Asperger syndrome. "This study aims to test the possible association between impaired levels of gamma aminobutyric acid (GABA), serotonin, dopamine, oxytocin, and interferon-γ-induced protein-16 (IFI16) and the severity of social and cognitive dysfunctions in individuals with autism spectrum disorders." (PMID 24400970, 2014).
B-cell lymphoma (1 paper, 2020). "Consistent with our results, primary effusion B-cell lymphoma cells showed that IFI16 mediated caspase-1 inflammasome activation." (PMID 32577124, 2020).
cardiomyopathy (1 paper, 2025). A disease of the heart muscle or myocardium proper. "Furthermore, reducing IFI16 levels directly mitigated markers of cell injury and enhanced viability in vitro, supporting a detrimental role for the DDR-IFI16 axis in contributing to both fibrosis and cellular damage in the context of cardiomyopathy." (PMID 40365289, 2025).
Cerebral ischemia (1 paper, 2025). Restriction of arterial blood supply to the brain associated with insufficient oxygenation to support the metabolic requirements of the tissue. "This aligns with reports of GPR30-mediated NLRP3 inflammasome suppression in cerebral ischemia and colitis models, though our study uniquely implicates IFI16/NLRC4 as key effectors in SAH." (PMID 40726812, 2025).
Chagas disease (1 paper, 2024). A parasitic infection caused by Trypanosoma cruzi. "Our study points to IFI204/IFI16 and BST2 as potential Chagas disease targets and SLAMF1 as their inhibitor through some unknown mechanism." (PMID 39000601, 2024).
cystic fibrosis (1 paper, 2017). Autosomal recessive disorder caused by pathogenic variants in the CFTR gene (cystic fibrosis transmembrane conductance regulator), which encodes a chloride and bicarbonate channel expressed in epithelial cells, and follow the diagnosis criteria. "We found that IFI16, CCNE2 and IGFBP2 are potential modifiers in the altered lung function in Cystic Fibrosis." (PMID 28339466, 2017).
esophageal cancer (1 paper, 2022). A primary or metastatic malignant neoplasm involving the esophagus. "Finally, RAN-Seq, qpcr, transwell assay were used to investigate the underlying mechanism of IFI16 in esophageal cancer metastasis." (PMID 35371314, 2022). "Then, cck8, transwell assay,mouse metastasis experiments were performed to determine the functional role of IFI16 in esophageal cancer." (PMID 35371314, 2022). "Compared with patients with esophageal cancer with low IFI16 expression, patients with high IFI16 expression had poorer relapse-free survival (RFS) (P=0.045)." (PMID 35371314, 2022). "The results suggested that IFI16 plays a key role in increasing esophageal cancer cell migration and invasion in vitro." (PMID 35371314, 2022). "Next, to evaluate the clinical relevance of IFI16, we conducted further research on IFI16 through immunohistochemistry (IHC) assays, which produced similar results, with an increase expression of IFI16 in esophageal cancer tissues as compared with paracancerous tissue." (PMID 35371314, 2022).
glioblastoma (1 paper, 2025). The most malignant astrocytic tumor (WHO grade IV). "Senescence-like phenotype mediated by IFI16 in glioblastoma (GBM) suppresses ferroptosis via Heme Oxygenase-1 (HMOX1) activation, conferring radiation resistance." (PMID 40801613, 2025).
hidradenitis suppurativa (1 paper, 2023). A chronic suppurative and cicatricial disease of the apocrine glands occurring chiefly in the axillae in women and in the groin and anal regions in men. "An association between replication stress and inflammation (by IFI16/STING pathway) has been shown in hidradenitis suppurativa (HS) patients." (PMID 37573368, 2023).
Immunodeficiency (1 paper, 2024). Failure of the immune system to protect the body adequately from infection, due to the absence or insufficiency of some component process or substance. "Altogether, whereas the associations with viral load were more complex and not significant for NLRP3, our data support that HIV infection induces IFI16 in human monocytes, and both IFI16 and NLRP3 expression is higher in PWH with more pronounced immunodeficiency (i.e., with lower CD4 T cell counts)." (PMID 39000248, 2024). "Furthermore, both IFI16 and NLRP3 correlated negatively with CD4 T cell counts, indicating decreased levels in relation to HIV-related immunodeficiency." (PMID 39000248, 2024).
Insulin resistance (1 paper, 2018). Increased resistance towards insulin, that is, diminished effectiveness of insulin in reducing blood glucose levels. "We believe that an elevated action of IFI202b/IFI16 leads to hypertrophic adipocytes, elevated fat storage, induction of inflammatory cytokine expression and finally insulin resistance and fatty liver." (PMID 29478099, 2018).
kidney cancer (1 paper, 2021). Primary or metastatic malignant neoplasm involving the kidney. "The wound scratch and transwell assays showed that kidney cancer cells with high IFI16 expression migrated and invaded faster than cells with low expression." (PMID 33659024, 2021).
laryngeal carcinoma (1 paper, 2020). Carcinoma that arises from the laryngeal epithelium. "The correlation between IFI16 and caspase-1 expression was further analyzed via immunohistochemistry for 36 biopsy specimens of laryngeal carcinoma tissues." (PMID 32577124, 2020). "The significantly increased expression of IFI16 (2.32 ± 0.12-fold), caspase-1 (1.85 ± 0.13-fold), and IL-1β protein (1.93 ± 0.10-fold) was detected in laryngeal cancer tissues compared with that in adjacent tissues." (PMID 32577124, 2020). "It was reported for the first time in this study that IFI16 was overexpressed and positively correlated with caspase-1 in laryngeal carcinoma tissues." (PMID 32577124, 2020). "Western blot was performed to test the expression of IFI16, caspase-1 and IL-1β protein in 3 pairs of primary laryngeal carcinoma and their normal para-laryngeal tissues collected from 3 patients with laryngeal cancer after surgery." (PMID 32577124, 2020). "According to the results of the previous work, the mechanism of DHA in regulating the crosstalk between IFI16 inflammasome and autophagy by inhibiting RalB expression was analyzed in order to provide clues for new therapeutic methods in laryngeal cancer." (PMID 32577124, 2020). "The mechanism of DHA in regulating the crosstalk between IFI16 inflammasome and autophagy by inhibiting RalB expression was analyzed in order to provide clues for new therapeutic methods in laryngeal cancer." (PMID 32577124, 2020). "It is concluded that DHA can inhibit the expression and/or activation of IFI16 inflammasome in laryngeal cancer cells." (PMID 32577124, 2020). "In line with this, the study firstly reported that IFI16 was correlated with caspase-1 in laryngeal cancer." (PMID 32577124, 2020). "The expression of IFI16 inflammasome in laryngeal cancer was further examined." (PMID 32577124, 2020). "Therefore, it was suggested that DHA inhibited the activation of IFI16 inflammasome in a concentration-dependent manner in laryngeal cancer Hep-2 cells." (PMID 32577124, 2020). "Therefore, IFI16 inflammasome was selected as a predictive target on laryngeal cancer." (PMID 32577124, 2020).
laryngeal squamous cell carcinoma (1 paper, 2020). A squamous cell carcinoma that arises from the larynx. "However, it is still unclear whether the IFI16 inflammasome is involved in human laryngeal squamous cell carcinoma." (PMID 32577124, 2020).
liver diseases (1 paper, 2018). "Here, we show for the first time that IFI16 expression levels are associated with liver inflammation in HBV-liver diseases." (PMID 29743020, 2018).
liver fibrosis (1 paper, 2024). "IFI16 has been previously reported to function in lung cystic fibrosis, while its role in liver fibrosis has scarcely been researched." (PMID 39257588, 2024).
lung adenocarcinoma (1 paper, 2022). A carcinoma that arises from the lung and is characterized by the presence of malignant glandular epithelial cells. "The single-stranded DNA (ssDNA) accumulated in the cytosol of SAMHD1-deficient lung adenocarcinoma (LUAD) cells, accompanied by upregulated DNA sensor IFN-γ-inducible protein 16 (IFI16) and activated STING pathway." (PMID 36578072, 2022).
metastatic tumors (1 paper, 2021). "DIRAS1, FBXL16, TP53I11, TFF2, and ZNF467 were upregulated in both metastatic tumors and GHSROS-overexpressing PC3 and LNCaP cells, while AASS, CHRDL1, CNTN1, IFI16, and MUM1L1 were downregulated." (PMID 33585078, 2021).
Miscarriage (1 paper, 2021). A pregnancy that ends at a stage in which the fetus is incapable of surviving on its own, defined as the spontaneous loss of a fetus before the 22th week of pregnancy. "Furthermore, studies have shown that changes in IFI16 gene expression in bovine endometrium lead to decreased embryo survival, further leading to miscarriage." (PMID 33535891, 2021).
ocular infection (1 paper, 2019). "A role for IFI16 in HSV infection has been assessed in vivo, with IFI16 knockdown mice unable to produce IFN-α and clear HSV-1 from the cornea after ocular infection." (PMID 31114761, 2019).
oral squamous cell carcinoma (1 paper, 2020). "Knockdown of either AIM2 or IFI16 in oral squamous cell carcinoma cells reduced cell growth." (PMID 32328125, 2020).
oropharyngeal squamous cell carcinomas (1 paper, 2019). "Positivity for p16 and IFI16 was observed by immunohistochemistry in 63.6% and 45.5% of oropharyngeal squamous cell carcinomas, respectively." (PMID 31861809, 2019). "The role of IFI16 as a restriction factor for HPV is of particular interest for HNSCC, since HPV has been detected in 22%–47% of oropharyngeal squamous cell carcinomas." (PMID 31861809, 2019).
Osteopenia (1 paper, 2019). Osteopenia is a term to define bone density that is not normal but also not as low as osteoporosis. "The levels of the mRNA for γ interferon inducible protein, IFI16, were determined in the PBMCs of osteopenia and osteoporosis patients." (PMID 31278293, 2019).
ovarian endometrioid adenocarcinoma (1 paper, 2017). An endometrioid adenocarcinoma arising from the ovary. "The positive expression of IFI16 was observed in ovarian serous adenocarcinoma patients but not in ovarian endometrioid adenocarcinoma ones." (PMID 28611294, 2017).
ovarian tumors (1 paper, 2019). "Lastly, we show that the combination of high mRNA expression levels for three IFN-γ target genes (CXCL10, CXCL11 and IFI16) correlated with overall survival in ovarian tumors from the TCGA database, pointing to the potential clinical significance of this pathway in HGSOC." (PMID 31840082, 2019).
Parkinson disease (1 paper, 2023). A progressive degenerative disorder of the central nervous system characterized by loss of dopamine producing neurons in the substantia nigra and the presence of Lewy bodies in the substantia nigra and locus coeruleus. "Likewise, the DNA sensor IFI16 detects released mtDNA in cellular models of Parkinson’s disease (PD) and induces a mixed inflammatory response." (PMID 37001140, 2023).
pneumococcal infection (1 paper, 2013). Infections with bacteria of the species streptococcus pneumoniae. "Furthermore, ASC is capable of binding and facilitating the function of several other inflammasomes (such as NLRC4 and IFI16), though the relevance of this during pneumococcal infection is not evident." (PMID 23902681, 2013).
promyelocytic leukemia (1 paper, 2016). "The most prominent factors in nuclear antiviral responses, which have been implicated in targeting incoming viral genomes, are components of promyelocytic leukemia nuclear bodies (PML-NBs) and the nuclear DNA sensor IFI16 (interferon gamma inducible protein 16)." (PMID 27782081, 2016).
Psoriasiform dermatitis (1 paper, 2016). A skin abnormality characterized by redness and irritation, with thick, red skin that displays flaky, silver-white patches (scales). "Importantly, knocking down p204, which is reported as the mouse orthologous of human IFI16, inhibited epidermal hyperplasia in mice with imiquimod-induced psoriasiform dermatitis." (PMID 27137868, 2016).
pulpitis (1 paper, 2021). Inflammation of the dental pulp. "Since IFN-γ cytokine may be implicated in the immune response during the process of pulp inflammation, the epigenetic events of pulpitis could also be relevant to the alteration of IFI16." (PMID 33777260, 2021).
Simpson-Golabi-Behmel syndrome (1 paper, 2018). Simpson-Golabi-Behmel syndrome is a rare X-linked multiple congenital anomalies syndrome, characterized by pre- and postnatal overgrowth, distinctive craniofacial features, variable congenital malformations, organomegaly and an increased tumor risk. "The impact of Ifi202b and its human orthologue IFI16 on adipogenesis was investigated by modulating their respective expression in murine 3T3-L1 and human Simpson-Golabi-Behmel syndrome (SGBS) pre-adipocytes." (PMID 29478099, 2018).
skin squamous cell carcinoma (1 paper, 2021). A carcinoma arising from the squamous cells of the epidermis. "Also, recent research confirmed that in the pathogenesis of skin squamous cell carcinoma, IFI16, which originally inhibited cell growth, suppressed its expression by methylation and acetylation and reversely promoted tumor growth." (PMID 34930258, 2021).
skin ulcerations (1 paper, 2021). "Surprisingly, high-level expression of IFI16 was detected in keratinocytes of histologically normal epidermal tissue, distal to the region of overt viral replication and skin ulcerations." (PMID 34552595, 2021).
teratocarcinoma (1 paper, 2019). A germ cell tumor characterized by the presence of an embryonal carcinoma component and a teratoma component. "Thus, a feature of stem cells, as well as teratocarcinoma cell lines with stem cell-like phenotype, could be the repression of IFI16 expression potentially to favor HERV expression during this developmental stage." (PMID 31333597, 2019). "Using western blotting and RNA-Seq analysis, we found that an ESC line derived from a teratocarcinoma (NCCIT) did not express IFI16." (PMID 31333597, 2019).
type 2 diabetic (1 paper, 2025). "Interestingly, a significant positive correlation existed between clinical periodontal parameters in type 2 diabetic patients, such as the gingival index, clinical attachment loss, periodontal inflamed surface area and salivary levels of AIM2, IFI16, and IL18." (PMID 41440367, 2025).